NR2E3 (nuclear receptor subfamily 2 group E member 3)
Diseases named in the same sentence as NR2E3 in open-access papers (continued):
Sharing a sentence is not in itself a finding about the gene and the disease.
enhanced S-cone syndrome (30 papers, 2006 to 2025). "Enhanced S-cone syndrome (ESCS) is a rare type of retinal dystrophy disorder that is linked to NR2E3 gene mutation and NRL gene mutations less widely." (PMID 37719593, 2023). "Pathogenic variants involving NR2E3 cause a spectrum of retinopathies, including enhanced S-cone syndrome, Goldmann-Favre syndrome, retinitis pigmentosa, and clumped pigmentary retinal degeneration, with limited evidence of genotype-phenotype correlations." (PMID 37510230, 2023). "Enhanced S-cone syndrome (ESCS) is a rare autosomal recessive retinal degeneration mainly associated with pathogenic variations in the NR2E3 gene." (PMID 36140584, 2022). "The missense mutation c.925C > T of NR2E3 is a novel mutation for Goldmann-Favre syndrome, but the c.925C > G (p.R309G) at the same location of mRNA and polypeptide chain is known to be pathogenic for Goldmann-Favre syndrome and enhanced S-cone syndrome." (PMID 33781268, 2021). "Mutations in NR2E3 have been linked with autosomal recessive IRDs such as Enhanced S-cone syndrome (ESCS, MIM 268100) and Goldmann-Favre syndrome (GFS, MIM 268100)." (PMID 31083481, 2019). "Enhanced s-cone syndrome is a rare, slowly progressive autosomal recessive retinal degeneration related to mutation in NR2E3." (PMID 23710333, 2013). "It is the same disease as the Enhanced S-Cone Syndrome (ESCS) due to mutations in NR2E3, that presents with characteristic whitish and secondarily round pigmented lesions in retinal periphery when evolved." (PMID 17032466, 2006). "Mutations in the nuclear receptor subfamily 2 group E member 3 (NR2E3) gene cause enhanced S-cone syndrome (ESCS) (OMIM 268100), a congenital retinal disease characterized by night blindness, hypersensitivity to short-wavelength light, and eventual loss of visual acuity." (PMID 38652563, 2024). "Conversely, loss-of-function variants in NRL have been found in patients affected by autosomal recessive clumped pigmentary retinal degeneration, which resembles the clinical phenotype caused by autosomal recessive variants in NR2E3, also known as enhanced S-cone syndrome (ESCS, OMIM #268100)." (PMID 39766861, 2024). "Enhanced S-Cone Syndrome (ESCS) and Goldmann–Favre syndrome are two distinct entities within the spectrum of retinal degenerative diseases, both caused by mutations in the NR2E3 gene." (PMID 40075868, 2025). "Enhanced S-cone syndrome (ESCS) is a very rare disease mainly associated with variants in the NR2E3 gene which has been reported to account for up to 93% of cases." (PMID 36140584, 2022). "Pathogenic NR2E3 mutations have been associated with enhanced S-cone syndrome (ESCS)/Goldman-Favre syndrome, clumped pigmentary retinal degeneration, as well as autosomal recessive and autosomal dominant RP." (PMID 32668775, 2020). "Enhanced S-cone syndrome (ESCS) is an autosomal recessive retinopathy that results from mutations in the photoreceptor cell transcription factor, NR2E3 (Nuclear Receptor Subfamily 2, Group E, Member 3)." (PMID 30959774, 2019). "As other NR2E3 mutations that have been found in autosomal recessive IRDs, such as enhanced S-cone syndrome (ESCS, MIM 268100), have a loss-of-function effect, we hypothesized that the c.166G>A allele could function as a therapeutic target for selective suppression." (PMID 31083481, 2019). "This study describes a typical midperipheral retinal thickening with coarse delineation on widefield OCT in an 11-year-old girl with the presumed diagnosis of enhanced S-cone syndrome (ESCS), attributed to the presence of a homozygous likely pathogenic variation in the NR2E3 gene." (PMID 41995403, 2024). "Enhanced S-cone syndrome (ESCS) is mainly associated with mutations in the NR2E3 gene." (PMID 29385733, 2018). "The nuclear receptor subfamily 2 group E member 3 (NR2E3) gene is implicated in several eye-related disorders including enhanced S-cone syndrome, a form of retinitis pigmentosa, and Goldmann-Favre syndrome." (PMID 28106113, 2017).
enhanced S-cone syndrome (continued). "NR2E3 is responsible for two main retinal phenotypes ESCS (including Goldmann-Favre syndrome) only for recessive forms and RP (including CPRD) related to both dominant and recessive forms." (PMID 26910043, 2016). "Mutations in the nuclear hormone receptor NR2E3, also known as photoreceptor-specific nuclear receptor (PNR), have been associated with several retinal diseases including enhanced S-cone syndrome (ESCS), Goldmann-Favre syndrome and retinitis pigmentosa." (PMID 24498227, 2014). "Mutations in the NRL and NR2E3 genes encoding rod-specific transcription factors exemplify this diversity, as autosomal dominant, autosomal recessive, and sporadic mutations have been implicated in RP and the related IRD, enhanced S-cone syndrome (ESCS)." (PMID 32668775, 2020). "The spectrum of clinical phenotypes with NR2E3 abnormalities is wide, and includes clumped pigmentary degeneration and autosomal dominant retinitis pigmentosa as well as ESCS and Goldmann-Favre Syndrome." (PMID 21364904, 2011). "The corresponding human disease, enhanced S-cone syndrome (ESCS), may either be caused by a lack of NRL or NR2E3, a transcription factor with overlapping functions to NRL." (PMID 19838301, 2009).
retinitis pigmentosa (23 papers, 2010 to 2025). Retinitis pigmentosa (RP) is an inherited retinal dystrophy leading to progressive loss of the photoreceptors and retinal pigment epithelium and resulting in blindness usually after several decades. "A missense variant of NR2E3, c.166G>A, p.(Gly56Arg) or G56R, was reported in 1–2% of retinitis pigmentosa cases." (PMID 38474086, 2024). "Mutations in the human NR2E3 gene, which encodes a retina-specific nuclear receptor, lead to enhanced S-cone syndrome and retinitis pigmentosa." (PMID 20454693, 2010). "•These data may stimulate further investigations comparing the molecular mechanisms of the two diseases caused by mutations in NR2E3, Retinitis Pigmentosa and Enhanced S-cone Syndrome, in humans and mice." (PMID 33163596, 2020). "Affecting approximately 1 in 4000 individuals worldwide, retinitis pigmentosa exhibits significant genetic heterogeneity, with mutations in genes such as RHO, PRPF31, RPE65, USH2A, and NR2E3, which contribute to its diverse clinical presentation." (PMID 40869487, 2025). "Expression of nuclear receptor Nr2e3 via AAV8-Nr2e3 gene therapy in multiple unique mouse models of retinitis pigmentosa (RP) and Leber Congenital Amaurosis (LCA) resulted in restoration of photoreceptor cells and improved retinal function." (PMID 38474086, 2024). "Nevertheless, to our knowledge this is the first report of NR2E3 pseudodominant inheritance in retinitis pigmentosa." (PMID 36832217, 2023). "For example, many genes with causative mutations leading to Retinitis Pigmentosa, including RHO, NRL, and NR2E3 demonstrated foveal rod enrichment." (PMID 32555229, 2020). "In conclusion, inhibition of the NRL/NR2E3 pathway represents an intriguing approach for the treatment of retinitis pigmentosa." (PMID 32668775, 2020). "Novel mutations in the genes NR2E3 and RGR could be related to retinitis pigmentosa and affect the phenotype; still these were not likely to be the main causative genes." (PMID 26229699, 2015).
retinal disease (17 papers, 2007 to 2025). "During development, Nr2e3 is a key regulator of photoreceptor specification and has been linked to multiple inherited retinal diseases such as RP and clumped pigmentary retinal degeneration." (PMID 40824246, 2025). "The rd7 mouse is a functional null representing varied phenotypes of recessive NR2E3-associated retinal disease that encompasses both RP and ESCS18,19,23,26,50." (PMID 39019967, 2024). "Here, we generated retinal organoids carrying retinal disease–causing variants in NR2E3, as well as isogenic and unrelated controls." (PMID 38652563, 2024). "Further studies will also investigate the effectiveness of NR2E3 therapeutic in other non-NR2E3-associated retinal diseases." (PMID 39019967, 2024). "The function of genetic modifiers of NR2E3, such as the nuclear hormone receptor Nr1d1 (Rev-erbα), has been explored as a therapeutic option in the NR2E3-associated retinal disease, rd7, mouse model." (PMID 32679203, 2021). "By virtue of these function-structure correlations, we propose that SD-OCT can allow for an informative, noninvasive assessment of NR2E3-associated retinal disease in live human patients." (PMID 33513943, 2021). "The association of NR2E3 with several clinical phenotypes and varying modes of inheritance strongly indicates that these retinal diseases manifest on a permissive or selective genetic background and are influenced, at least in part, by genetic modifier genes." (PMID 32123325, 2021). "Clinical studies have identified a range of variants in the NR2E3 gene coding sequence associated with human retinal disease." (PMID 28300834, 2017). "The results of this pharmacology study are translational to dosage selection of NR2E3 as a therapeutic agent, longitudinal therapeutic effectiveness, and treatment effectiveness in early and intermediate stage NR2E3-associated retinal disease in clinical trials." (PMID 39019967, 2024). "Interestingly, NR2E3 as a genetic modifier directly can serve as a therapeutic target to treat inherited retinal diseases including NR2E3-associated retinopathies." (PMID 37181651, 2023). "Interestingly, several recent reports have demonstrated that loss of AHR caused development of retinal degenerative diseases similar to the retinal diseases caused by NR2E3 depletion." (PMID 28878246, 2017). "The retinal degeneration 7 (rd7) mouse is a model for Nr2e3 associated retinal disease." (PMID 24498227, 2014). "Interestingly, GC1 and the nuclear hormone receptor Nr2e3 shown to regulate Ankmy2 expression in mouse retina both harbor mutations in patients with retinal disease." (PMID 21124868, 2010). "In addition, our prior and current studies show that regardless of the vehicle (naked DNA, nanoparticle, AAV8, AAV5, or AAV2.7m8), Nr2e3 can rescue retinal disease in rd7." (PMID 32123325, 2021). "In addition to this, we also detected differentially expressed genes directly ascribed to retinal diseases such as Klhl23 or Nr2e3 involved in cone-rod dystrophies or RP, respectively." (PMID 29847644, 2018). "While these features make NR2E3 a potential therapeutic target for the treatment of retinal diseases, there has been a clear lack of structural information for the receptor." (PMID 24069298, 2013).
Retinal dystrophy (16 papers, 2007 to 2025). Retinal dystrophy is an abnormality of the retina associated with a hereditary process. "We found downregulation of Prdm1—a photoreceptor marker—and Nr2e3—a key regulator of photoreceptor specification also implicated in retinal dystrophies—as well as effects on NR2E3’s direct and indirect targets." (PMID 40824246, 2025). "Markedly, we found that PRDM13 expression downregulated the photoreceptor marker Prdm1 as well as Nr2e3—a key regulator of photoreceptor specification also implicated in retinal dystrophies—and affected NR2E3’s direct and indirect targets." (PMID 40824246, 2025). "Many of these mutations fall into genetic pathways implicated in retinal functioning, particularly the NR2E3 gene that has been implicated in several inherited retinal dystrophies." (PMID 38392207, 2024). "NR2E3 variants were identified in three patients, from unrelated families, who had been diagnosed with retinal dystrophy." (PMID 33138239, 2020). "Retinal dystrophies associated with the gene NR2E3 (nuclear receptor subfamily, 2 group, E member 3) can be inherited as either autosomal recessive or dominant." (PMID 33138239, 2020). "Most NR2E3 mutations that cause retinal dystrophy affect amino acid residues located in these two domains." (PMID 22128245, 2011). "Patients with NR2E3 dominant mutation showed a moderate form of retinal dystrophy." (PMID 26910043, 2016). "The retinal changes with a clumped pattern at the level of the RPE, mainly along the temporal vascular arcades, are typical for NRL- or NR2E3-related retinal dystrophy." (PMID 39766861, 2024). "NR2E3 is predominantly known for its role in the differentiation and development of retinal photoreceptors, which are related to retinal dystrophies." (PMID 38480634, 2024). "In a second case suffering from PPHCD, a standardized SPARK Inherited Retinal Dystrophy (IRD) panel was performed testing several mutations of indeterminate significance across multiple genes, including CCD2D2A, CEP78, NR2E3, PCARE, PEX14, and RPGRIP1." (PMID 38392207, 2024). "Two siblings from a family with known consanguinity (#3, #4) presented with a history of vision problems and a retinal phenotype compatible with NR2E3-related retinal dystrophy, which is unrelated to systemic oxalosis." (PMID 36260161, 2023). "Further, three genes, ABCA4, MYO7A and NR2E3, are shown to have an association to PRC thickness and have a prior association with retinal dystrophies." (PMID 36848389, 2023). "So far, retinal organoids derived from patient-specific iPSC were reported to model, at some degree, phenotypes of retinal dystrophy, such as CEP290 and NR2E3 gene mutation-related LCA." (PMID 31572124, 2019). "The subnetwork retrieved after querying for three retinal-specific transcription factors (shortest path between NRL and NR2E3, plus addition of CRX) allows showing their connection to other causative retinal dystrophy genes." (PMID 31712826, 2019).
autosomal dominant retinitis pigmentosa (8 papers, 2009 to 2023). Autosomal dominant retinitis pigmentosa (RP) is an autosomally dominant inherited retinal dystrophy leading to progressive loss of the photoreceptors and retinal pigment epithelium and resulting in blindness usually after several decades. "The aim of this study is to analyse the frequency of the p.Gly56Arg mutation in NR2E3 for the largest cohort of autosomal dominant Retinitis Pigmentosa patients to date and its associated phenotype." (PMID 26910043, 2016). "While most NR2E3 mutations have a recessive mode of inheritance, a c.166G>A (p.G56R) mutation in the NR2E3 gene is associated with autosomal dominant retinitis pigmentosa." (PMID 24498227, 2014). "The recurrent missense variant in Nuclear Receptor Subfamily 2 Group E Member 3 (NR2E3), c.166G>A, p.(Gly56Arg) or G56R, underlies 1%–2% of cases with autosomal dominant retinitis pigmentosa (adRP), a frequent, genetically heterogeneous inherited retinal disease (IRD)." (PMID 31083481, 2019). "The NR2E3 gene is associated with both autosomal recessive and dominant retinitis pigmentosa." (PMID 26910043, 2016). "This research is the single largest NR2E3 genotype-phenotype correlation study performed to date in autosomal dominant Retinitis Pigmentosa." (PMID 26910043, 2016). "There are at least five genes, RHO, NRL, NR2E3, CRX, and RP1, associated with both autosomal dominant retinitis pigmentosa (ADRP) and autosomal recessive retinitis pigmentosa (ARRP)." (PMID 25692141, 2015). "In humans, mutations in NR2E3 have been associated with the recessively inherited enhanced short wavelength sensitive (S-) cone syndrome (ESCS) and, more recently, with autosomal dominant retinitis pigmentosa (adRP)." (PMID 19823680, 2009).
breast carcinoma (8 papers, 2016 to 2025). "Together with positive associations between NR2E3 and recurrence-free survival in ER+ breast cancer and overall survival in liver cancer, these findings suggest NR2E3’s potential role as a tumor suppressor." (PMID 39809731, 2025). "Previously, we reported that higher NR2E3 levels are strongly associated with good clinical outcomes in breast cancer by maintaining the expression of estrogen receptor α (ESR1), a major guideline for breast cancer prognosis and treatment." (PMID 28878246, 2017). "High expression levels of PNR/NR2E3 have also been associated with longer recurrence-free survival in breast cancer patients and enhanced response to tamoxifen treatment." (PMID 27158822, 2016). "NR2E3 was considered to regulate the expression of the estrogen receptor in breast cancer cells via binding to its promotor." (PMID 38480634, 2024). "Limited functional data on NR2E1 and NR2E3 are available and only few pertain to the breast-cancer realm." (PMID 26894976, 2016). "NR2E3 has previously been defined as a photoreceptor-specific nuclear receptor, acting as an essential character in the development of normal retina as well as in the suppression of liver and breast cancer." (PMID 38480634, 2024). "Low levels of NR2E1-mRNA and NR2E3-mRNA are detectable in mammary-glands and NR2E1 is further down-regulated in breast-cancers." (PMID 26894976, 2016). "The group of NRs endowed with potential oncogenic properties in breast-cancer is smaller and consists of the Lipid-Sensors, NR1C2 and NR1I2, the Enigmatic-Orphans, NR1F3, NR3B1 and NR5A2, as well as the Orphan-Receptors, NR2E1, NR2E3 and NR6A1." (PMID 26894976, 2016).
night blindness (7 papers, 2012 to 2025). Inability to see clearly in dim light. "Considerable phenotypic variability is a feature of NR2E3 mutations although features of the NR2E3-linked recessive disorders include night blindness in early stages, clumped pigmentary deposits, and a more severe loss of rods than cones." (PMID 22605927, 2012). "The patient presented with retinoschisis, macular oedema and night blindness, and was a homozygous carrier of NR2E3 c.925C > T (p.R309W)." (PMID 33781268, 2021). "In humans, disruption of either NRL or NR2E3 expression causes enhanced S-cone syndrome, characterized by supranormal blue cone function due to an increased proportion of S-cones and night blindness due to the absence of rod-photoreceptors." (PMID 40758714, 2025). "Mutations in the NR2E3 gene are associated with enhanced S-cone syndrome (ESCS) in patients which manifests as increased sensitivity to blue light (mediated by S-cones), and night blindness (due to rod defects)." (PMID 23650562, 2013). "Mice lacking NR2E3 (Nr2e3rd7/rd7 referred to here as rd7) are a model for enhanced S-cone syndrome, a disease associated with increased sensitivity to blue light and night blindness." (PMID 23650562, 2013). "The NR2E3 gene recessive mutations present variable phenotypes (ESCS, GFS and CPRD) with variable ophthalmological findings, but all showing night blindness, rudimental or absent rod function, and hyperfunction of the "blue" S-cones." (PMID 26910043, 2016).